PCNA (proliferating cell nuclear antigen)
Diseases named in the same sentence as PCNA in open-access papers (continued):
Sharing a sentence is not in itself a finding about the gene and the disease.
infection (continued). "Our data suggest that the accessory components (RFC2, RFC3, RFC5, PCNA), polymerases (POLD1, POLD2, POLD3, POLE, POLE2, POLE4), and ligase LIG1, were downregulated during infection, for which the downregulation of RFC5, POLD1, POLD2, POLD3, POLE, and LIG1 was CagA-related." (PMID 33339161, 2020). "From 5 to 25 days post-infection (dpi), mouse lungs were subjected to histopathologic and immunofluorescence analysis to probe for global distribution of lung repair cells (using P63 and KRT5 markers for DASCs; SPC and PCNA markers for AT2 cells)." (PMID 31455003, 2019). "ORFV infection resulted in downregulation of K1, K10, and loricrin at the transcriptional level without affecting proliferation as shown by PCNA or Ki-67 expression." (PMID 30699132, 2019). "Similarly to what was observed in mouse cells, infection with a WT MCMV induced the expression of the E2F target genes Cyclin E1 and PCNA, and to a lower extent of Cyclin A2." (PMID 30532172, 2018). "For example, on day 4 after LCMV-WE infection, ~25% of hepatocytes were positive for PCNA staining (i.e., not G0)." (PMID 25822203, 2015). "At 16 hours after infection, BLM transcript levels increased slightly in pm975-infected cells, but not others, whereas PCNA mRNA was elevated for all infections." (PMID 26448631, 2015). "Chromatin-bound PCNA, DNA polymerase δ, and the clamp-loader RFC, host proteins that are essential for viral DNA replication in vitro, colocalized with Tag foci in both BSC40 and human U2OS cells at 48 hours post infection (hpi)." (PMID 23592994, 2013). "Results: 31 (43.7%) cases showed infection of HPV and 38 (53.5%) showed overexpression of PCNA." (PMID 24353714, 2013). "Expression of PCNA in the liver hepatocytes of both infected and non-infected mice at days 2 and 8 after infection clearly shows the regeneration process induced by the injection in the liver, which constitutes, per se, a liver injury." (PMID 22253905, 2012). "Thus, the immunodetection of PCNA by current immunohistochemical methods in the non-glandular and glandular parts of the stomach was sufficient to be used as an indicator of infection." (PMID 39296435, 2024). "However, when added before infection, PCNA-I1 does not impact PCNA levels on viral DNA, indicating that it can still be loaded onto viral DNA." (PMID 37486931, 2023). "Interestingly, on forced expression of SF1, cells (irrespective of the source) had a lower proliferation rate, as assessed by the expression of proliferating cell nuclear antigen (PCNA) and direct cell counting, and became proliferation arrested three to five days after infection." (PMID 29386111, 2018). "Thus, we investigated whether MVM-dependent depletion of p21 during infection, mediated by the CRL4Cdt2 E3 ubiquitin ligase, promoted efficient replication of the MVM genome by abrogating its inhibition of PCNA." (PMID 24699724, 2014). "Therefore, PCNA does not impact viral gene expression early during infection." (PMID 40130902, 2025). "Notably, an elevated expression of the proliferating cell nuclear antigen gene (pcna) was observed at 12, 24, and 48 hpi compared to its uninfected AGS cell control, while a reduced expression of pcna was examined at 48 hpi in infection-III and -IV in comparison to infection-I and -II." (PMID 34585958, 2021). "Therefore, PCNA restricts HCMV replication and genome synthesis, and the PCNA-mediated restriction of viral genome synthesis and progeny production was less apparent at higher MOIs of infection but not fully overcome." (PMID 40130902, 2025).
infection (continued). "Additionally, EnAd infection led to the up- and down-regulation of host genes not directly related to the HIF-pathway such as Proliferating Cell Nuclear Antigen (PCNA) and TATA-box Binding Protein (TBP) in both hypoxic and normoxic cultures, respectively (Figure A3C)." (PMID 32244697, 2020).
adenocarcinoma (15 papers, 2012 to 2025). A common cancer characterized by the presence of malignant glandular cells. "We found similar results in TCGA adenocarcinoma, squamous NSCLC, and HCC cohorts, with CRhi-like tumors enriched for the cell-cycle pathway and significantly higher PCNA expression compared with CRlo-like tumors." (PMID 35838048, 2022). "We examined the expression of several proteins involved in proliferation (PCNA), apoptosis (PARP, caspase-3, BAX, BCL-2, and BCL-XL and mammary carcinogenesis (ERα and HER2) in carefully selected representative sentinel adenocarcinomas from each diet group." (PMID 24465421, 2014). "However, in individual pERK1/2‐positive adenocarcinoma cells, the expression of PCNA was not always high, and various adenocarcinoma cells with different expression (e.g., only PCNA or only pERK1/2 or either strong and weak) were also admixed." (PMID 26864819, 2016).
colon polyps (5 papers, 2012 to 2021). "Western blot analysis showed that the expression of PCNA was reduced by 70.3% (p < 0.01 vs. vehicle control) and 79.9% (p < 0.01 vs. vehicle control), in small intestinal and colonic polyps, respectively." (PMID 27507058, 2016). "IHC analysis revealed a 73.1% reduction of PCNA stained cells in small intestine polyps (p < 0.01 vs. vehicle control), and a 84.1% reduction of PCNA stained cells in colonic polyps (p < 0.01 vs. vehicle control)." (PMID 27507058, 2016). "In addition, PCNA also plays an important role in the post-traumatic repair of many intestinal diseases." (PMID 34679029, 2021).
neurodegenerative disease (4 papers, 2014 to 2025). A disorder of the central nervous system characterized by gradual and progressive loss of neural tissue and neurologic function. "Re-expression of these cell cycle-related proteins, including cyclin A and PCNA, activates cell cycle events in post-mitotic neurons, and leads to cell death and neurodegenerative diseases (Yang and Herrup, 2007)." (PMID 31080801, 2019). "PCNA plays key roles in maintaining genome stability, coordinating oxidative stress responses, and facilitating DNA repair in neurons, particularly in the context of neurodegenerative diseases and injury." (PMID 40810764, 2025). "ATLD2 is a neurodegenerative disease based on defects in DNA repair due to an impaired PCNA." (PMID 37511614, 2023). "The DNA replication mediated by PCNA-DNA pol-β complex may be the missing link between the ectopic cell cycle events and neuronal death in PD and other neurodegenerative diseases." (PMID 25184665, 2014).
benign tumors (3 papers, 2004 to 2013). "Moreover, significantly higher levels of PCNA-PI were observed in malignant than in the benign tumors (t=−4.6323, P=0.0000)." (PMID 23599795, 2013).
colon (3 papers, 2010 to 2019). "Overexpression of PCNA was a common event in chemical carcinogen-induced colon carcinogenesis in previous studies." (PMID 31509964, 2019).
Connective Tissue Diseases (3 papers, 2010 to 2022). "Serum Connective Tissue Diseases screen: Negative (tested for U1RNP, SS-ARo (60 kDa, 52 kDa), SS-B/La, Centromere B, Scl-70, Jo-1, Fibrillarin, RNA Pol III, Rib-P, PM-Scl, and PCNA, Mi-2 proteins and Sm proteins and dsDNA)." (PMID 24955116, 2014).
bacterial infection (2 papers, 2017 to 2022). "No parasite or bacterial infection was involved in our study, but our PCNA and BrdU immunohistochemistry studies provided clear evidence of active proliferation activity and with quite a dramatic speed and magnitude." (PMID 28380006, 2017).
head and neck tumors (2 papers, 2013 to 2018). "PCNA has been shown to be a useful marker for the proliferating fraction of cells in various head and neck tumors." (PMID 29508125, 2018).
kidney (2 papers, 2020 to 2022). "We also identified BRCA1 and PCNA to be specifically over-represented in LUAD lung lesions and markedly correlated with lung LUAD patient survival." (PMID 33097805, 2020).
CNS tumors (1 paper, 2025). "A direct correlation is also observed between the levels of expression of PCNA (Proliferating Cell Nuclear Antigen) and the histological grade of CNS tumors; PCNA, in fact, is used to evaluate malignancy in CNS tumors and estimate the probability of relapses." (PMID 40507925, 2025).
genetic disease (1 paper, 2023). "Recently, a rare genetic disease, PCNA-associated DNA repair disorder (PARD; alternative name: Ataxia-Telangiectasia–like disorder 2) was reported in four individuals homozygous for the hypomorphic PCNA-S228I variant." (PMID 36990216, 2023).
inflammatory myopathy (1 paper, 2025). "Electromyoneurography (EMNG) confirmed inflammatory myopathy, while autoimmune serology was positive for antinuclear antibody (ANA), anti-Ro52, anti-SSA, and anti-proliferating cell nuclear antigen (PCNA) with marked hypocomplementemia." (PMID 41458824, 2025).
neurological diseases (1 paper, 2015). "Ingenuity Pathway Analysis revealed that these autoantigens were enriched for functions involved in neurological diseases (score = 43).Anti-proliferating cell nuclear antigen (PCNA) was found in the CSF of NPSLE and non-NPSLE patients." (PMID 25954975, 2015).
reproductive system diseases (1 paper, 2021). "This review summarizes the significance of the latest research on PCNA expression in reproductive system diseases." (PMID 34721621, 2021).
retinopathy (1 paper, 2021). "Our data revealed that up-regulation of CYP2J2 inhibited HRVEC viability, reduced the expression of PCNA, and inhibited migration; however, Terfenadone induced opposite effects on HRVEC viability and migration in hypoxia-induced retinopathy." (PMID 34666595, 2021).
PCNA also shares sentences with these, for which no sentence is quoted: multiple myeloma (7 papers); Alzheimer disease (5); scleroderma (5); ataxia-telangiectasia-like disorder (4); autoimmune disease (3); Erythema (3); esophageal squamous cell carcinoma (3); head and neck cancer (3); Autoimmunity (2); brain neoplasms (2); breast invasive carcinoma (2); cervicitis (2); chronic cervicitis (2); Cockayne syndrome (2); follicular lymphoma (2); Hodgkin’s disease (2); Human papillomavirus infection (2); Hyperinsulinemia (2); Hyperkeratosis (2); inflammatory bowel disease (2); Keratocystic odontogenic tumor (2); kidney diseases (2); Myocardial fibrosis (2); pancreatic adenocarcinoma (2); premature ovarian failure (2); Right ventricular hypertrophy (2); T-cell lymphomas (2); abortion (1); Acromicric dysplasia (1); age (1).
A further 111 diseases each share a sentence with PCNA in 1 paper.